FTH1 (ferritin heavy chain 1)
Description:
Stores iron in a soluble, non-toxic, readily available form. Important for iron homeostasis. Has ferroxidase activity. Iron is taken up in the ferrous form and deposited as ferric hydroxides after oxidation. Also plays a role in delivery of iron to cells (By similarity). Mediates iron uptake in capsule cells of the developing kidney (By similarity). Delivery to lysosomes is mediated by the cargo receptor NCOA4 for autophagic degradation and release of iron.
Synonyms: FTH; FTHL6; PIG15; PLIF; FHC; HFE5; NBIA9
Tractability: Small molecule: a structure with a bound ligand is known. Antibody: its Gene Ontology location is reachable by antibodies, with high confidence. PROTAC: ubiquitination databases record sites on it; its protein half-life has been measured.
Target class: Enzyme; Oxidoreductase
Gene: Protein-coding gene on chromosome 11 (61,959,718 to 61,967,634, reverse strand). Ensembl gene ENSG00000167996.
Subcellular location: Cytoplasm; Lysosome; Cytoplasmic vesicle, autophagosome
Subcellular location (Human Protein Atlas): Vesicles; Cytosol
Pathways (Reactome):
Vesicle-mediated transport: Golgi Associated Vesicle Biogenesis; Scavenging by Class A Receptors
Immune System: Neutrophil degranulation
Transport of small molecules: Iron uptake and transport
Gene Ontology:
Molecular function: ferrous iron binding; ferroxidase activity; identical protein binding; iron ion sequestering activity; protein binding; ferric iron binding; iron ion binding
Biological process: negative regulation of ferroptosis; negative regulation of fibroblast proliferation; autophagy; erythrocyte differentiation; immune response; intracellular iron ion homeostasis; iron ion transport; negative regulation of cell population proliferation
Cellular component: autolysosome; cytoplasm; cytosol; extracellular exosome; ferritin complex; lysosome; nucleus; extracellular region; ficolin-1-rich granule lumen; tertiary granule lumen; autophagosome
Genetic constraint (gnomAD): Loss-of-function variants: 3 observed, 19.58 expected, observed/expected ratio (o/e) 0.15, 90% interval 0.069 to 0.4. The upper end of that interval is the gene's LOEUF score, 0.4, which puts it in group 1 of 6, group 1 being the genes least tolerant of losing a copy. Missense variants: 143 observed, 213.5 expected, observed/expected ratio (o/e) 0.67, 90% interval 0.58 to 0.77. Synonymous variants: 81 observed, 85.87 expected, observed/expected ratio (o/e) 0.94, 90% interval 0.79 to 1.13.
Gene-disease validity (ClinGen):
ClinGen rates the evidence that FTH1 causes each of these diseases.
neurodegeneration with brain iron accumulation 9 (autosomal dominant): Moderate.
hemochromatosis type 5 (autosomal dominant): Limited.
Homologues: Orthologues: chimpanzee FTH1 (100% identical), macaque FTH1 (99% identical), dog FTH1 (96% identical), guinea pig FTH1 (95% identical), mouse Fth1 (92% identical), tropical clawed frog ftmt (78% identical), zebrafish fth1a (75% identical), zebrafish fth1b (73% identical), Caenorhabditis elegans ftn-2 (57% identical), Caenorhabditis elegans ftn-1 (51% identical). Paralogues in human: FTMT (80% identical), FTHL17 (64% identical), FTL (54% identical).
Diseases named in the same sentence as FTH1 in open-access papers:
FTH1 is named in the same sentence as 230 diseases in open-access papers, as found by Europe PMC text mining. Sharing a sentence is not in itself a finding about the gene and the disease. The quoted sentences say what the papers report.
breast carcinoma (50 papers, 2013 to 2026). "In breast cancer, serum biomarkers (CA 15-3) combined with tumor-associated antigens and autoantibodies (heterogeneous nuclear ribonucleoproteins F and FTH1) can improve the accuracy of breast cancer diagnosis." (PMID 38025726, 2023). "We performed the stemness feature analysis on pan-cancer and found that FTH1 expression was associated with the stemness features in many types of cancer including breast cancer." (PMID 36307127, 2023). "Fth1 levels are associated with the progression of breast cancer and chemo-sensitivity of breast cancer cells." (PMID 34295823, 2021). "FTH1 was shown to be a prognostic marker for triple-negative breast cancer (BC) patients and associated with an enrichment of CD8+ effector T cells." (PMID 38201455, 2023). "FTH1 nanoparticles coated with EGF have been successfully applied to breast cancer in vitro and in vivo." (PMID 38025726, 2023). "Low FTH1 expression is known to make breast cancer cells radiosensitive, and its higher expression is correlated with radioresistance." (PMID 36661191, 2023). "Epigenetically regulated, DNA methylation-based stemness was negatively correlated (Pearson correlation: P-value = 2.01e−02) with the gene expression of FTH1 in breast cancer (n = 774)." (PMID 36307127, 2023). "Ali and colleagues demonstrated that FTH1 silencing promoted cell growth in breast cancer leading to an increased c-MYC expression and reduced cell sensitivity to chemotherapy." (PMID 38001941, 2023). "After down-regulating FTH1 in breast cancer, cervical cancer and non-small cell lung cancer, cancer cells tend to be in a mesenchyme state, which helps tumor metastasis." (PMID 38025726, 2023). "Epigenetically regulated RNA expression-based stemness was positively correlated (Pearson correlation: P-value = 2.97e−02) with the gene expression of FTH1 in breast cancer (n = 1080)." (PMID 36307127, 2023). "The regulation of iron depletion by FTH1 can slow down the self-renewal of breast cancer stem cells, while silencing FTH1 in SKOV3 cells can promote the stemness of cervical cancer cells and the up-regulation of NANOG, SOX2, OCT4." (PMID 38025726, 2023). "In prostate and breast cancer, FTH1 can regulate immunity and inhibit cell apoptosis through the JNK signaling pathway." (PMID 37304234, 2023). "FTH1 can be used as a tumor promoter in metastatic melanoma cells, brain cancer, pancreatic cancer (Su, Lei & Zhang, 2017) and a tumor suppressor in non-small cell lung cancer and ovarian cancer, while the role of FTH1 in breast cancer is still controversial." (PMID 38025726, 2023). "While this has not been observed for FTL yet, it has been reported, that co-targeting of BRD4 and RAC1 disrupts the MYC/G9a axis and enhances the expression of FTH1 in breast cancer cells." (PMID 36231049, 2022). "FTH1 functions as a neoplastic suppressor in non-small cell lung cancer, breast cancer, and ovarian cancer." (PMID 34853622, 2021). "It is also reported that SF in malignant histiocytosis is mainly composed of FTH1, whereas SF in breast cancer patients is highly correlated with FTL26–28." (PMID 34711879, 2021). "We observed high expression of FTH1 in JIMT1 HER-2 positive breast cancer cells as compared with other breast cancer subtypes." (PMID 34803511, 2021). "In human breast cancer cell lines, a piRNA called piR-FTH1 shows an inverse correlation with the expression of Fth1 (ferritin heavy chain 1)." (PMID 33419460, 2021). "Elevated nuclear FTH1 in breast cancer cells, as a result of reduced miR-200b was proposed to protect DNA against oxidative damage, therefore, miR-200b replacement sensitized the cells to the DNA-damaging agent doxorubicin." (PMID 32328462, 2020). "In breast cancer cell lines expression of FTH1 and FTL mRNA and protein were low in cells with an epithelial phenotype and high in cells with a more aggressive mesenchymal phenotype." (PMID 32328462, 2020).
breast carcinoma (continued). "Autoantibodies were significantly higher in breast cancer patients relative to controls (P < 0.01), with an AUC of 0.73 and 0.69 for hnRNPF and FTH1 autoantibodies, respectively." (PMID 25143958, 2014). "Other genes affected by MPs in breast cancer include FTH1, PTP4A2, and TMBIM6." (PMID 41378310, 2025). "This research enables FTH1-mediated tumor MRI visualization and targeted therapy, providing a multimodal approach for gliomas, which also holds significant reference value for the treatment of pancreatic cancer, breast cancer, and other related malignancies." (PMID 40723232, 2025). "Also FTH1 was repeatedly discussed in the context of breast cancer and it was shown that ferritin stimulates breast cancer cells through an iron-independent mechanism and is localized within tumor-associated macrophages." (PMID 38940181, 2024). "In addition, FTH1 exerts significant antigrowth effects in breast cancer cells by inhibiting the expression of c-MYC." (PMID 38069262, 2023). "First, since FTH1 degradation is an important mechanism in TetC-induced breast cancer cell death, whether FTH1 overexpression alters TetC cytotoxity in breast cancer cells deserves further study." (PMID 35614944, 2022). "Additionally, some researches have revealed the anti‐growth and apoptosis‐promoting effects of FTH1 on breast cancer cells and non‐small cell lung cancer cells, further illustrating the existence of inconsistency among different cells." (PMID 35441429, 2022). "In light of recent work implicating FTH1 in the prognosis of breast cancer, we can speculate whether similar outcomes could be observed in cancers such as breast cancer cells if exposed to SPH and an appropriate breast cancer therapeutic." (PMID 35447901, 2022). "Recent observations in preclinical breast cancer models suggest that FTH1 is a significant tumor suppressor by inhibiting the expression of key oncogenes, such as c-MYC, and that its increased expression signifies a favorable prognosis and response to chemotherapy." (PMID 35447901, 2022). "Moreover, we tested the expression pattern of FTH1 in different molecular subtypes of breast cancer." (PMID 34803511, 2021). "Mechanistically, combined inhibition of BRD4-RAC1 signaling pathways targeted c-MYC-G9a-FTH1 axis and revealed a novel molecular mechanism that might play important role in inhibition of breast cancer progression." (PMID 34803511, 2021). "Overexpression of ferritin heavy chain (FTH1) often associates with good prognosis in breast cancer (BCa), particularly in the triple‐negative subtype (triple‐negative breast cancer)." (PMID 34551213, 2021). "Next, we investigated protein-protein interactions between c-MYC, G9a and FTH1 to test whether these proteins form complex in breast cancer cells." (PMID 34803511, 2021). "Both IRP1 and IRP2 are over-expressed in breast cancer, but only the overexpression of IRP2 is associated with decreased FTH1 and increased TFR1, resulting in an increase in the LIP, which may contribute to poor prognosis of some breast cancer patients." (PMID 29789480, 2018). "The expression and localization of ferritin-heavy chain (FTH1), the catalytic subunit of ferritin, was shown to predict survival for triple-negative breast cancer (BC) patients and be related to T-cell response." (PMID 38201455, 2023). "Six ferroptosis-related genes (SLC7A11, GPX4, FTH1, NQO1, NFE2L2, SQSTM1) demonstrated consistent upregulation across all breast cancer subtypes, with higher expression observed in more aggressive tumors." (PMID 42074090, 2026). "In breast cancer models, polypropylene increased AP2M1, PTP4A2, and TMBIM6 while reducing FTH1, a pattern consistent with enhanced trafficking/ER-stress signaling and diminished iron-mediated tumor suppressive functions." (PMID 41378310, 2025). "At the protein level, FTH1, ISCU, and SOCS1 were medium stained in breast cancer tissues on the Human Protein Atlas (HPA) portal." (PMID 40463869, 2025).
breast carcinoma (continued). "The expression of FTH1 in MCF-7, MDA-MB-231 and BT549 breast cancer cells was lower than that in SKBR3, JIMT-1 and MDA-MB-468." (PMID 34803511, 2021). "Similar to chemotherapy and iron chelation, increased expression of ferritin heavy chain 1 (FTH1) suppresses the expression of cellular myelocytomatosis and G9a in breast cancer (BCa) cells." (PMID 34551213, 2021). "For example, siRNA-mediated FTH1 knockdown decreased the LD50 of carmustine from 100 to 40 μM in U-251 glioblastoma cells, and similar depletion of FTH1 and FTL by miR-200b lowered the IC50 of doxorubicin from 20 to <5 μM in MDA-MB-231 breast cancer cells." (PMID 28793787, 2018). "In patients with breast cancer, for instance, increases in SF are strongly correlated with FTL rather than with FTH1, whereas these increases may be due to FTH1 overexpression in patients with acute myeloid leukemia (AML)." (PMID 39294443, 2024). "Taken together, our study identified a novel and potential therapeutic strategy by combined inhibition of BRD4-RAC1 signaling to suppress breast cancer development and tumorigenesis via c-MYC/G9a/FTH1 axis and down regulation of HDCA1 in different molecular subtypes in a context-dependent manner." (PMID 34803511, 2021).
glioma (32 papers, 2015 to 2026). A benign or malignant brain and spinal cord tumor that arises from glial cells (astrocytes, oligodendrocytes, ependymal cells). "High expression of ferritin heavy chain 1 (FTH1) has been associated with high-grade gliomas and poor prognosis in glioblastoma." (PMID 37082446, 2023). "In addition, higher expression of OGT, FOXC1, ASNS, GPT2, CBS, or FTH1 was also associated with poorer outcomes in clinical cases with renal clear cell carcinoma or glioma." (PMID 40416363, 2025). "Additionally, the decreased expression of FTH1 induced by orexin‐A leads to the deficiency of iron storage function, which increases the unstable iron in gliomas, providing a crucial foundation for the induction of ferroptosis." (PMID 38685674, 2024). "This study aimed to develop a chimeric element-regulated ferritin heavy chain 1 (FTH1) reporter system to enhance MRI-based glioma detection while enabling targeted therapy via transferrin receptor (TfR)-mediated drug delivery." (PMID 40723232, 2025). "In vitro and in vivo experiments validated that the chimeric element significantly enhances the specific expression of the MRI reporter gene FTH1 in gliomas, thereby achieving improved contrast imaging on MR T2-weighted images." (PMID 40723232, 2025). "Both in vitro and in vivo experiments confirmed that this chimeric component significantly enhances the specific expression of the MRI reporter gene FTH1 in gliomas." (PMID 40723232, 2025). "Since ferroptosis-related genes including xCT, GPX4 and FTH1 present as targets of Nrf2, many treatments seek to disturb ferroptosis by manipulating Nrf2 in gliomas." (PMID 39309434, 2024). "For instance, Taurine upregulated 1 (TUG1) targets MAZ and negatively regulates FTH1 expression, thereby strengthening the anti-glioma effect of DHA108." (PMID 39309434, 2024). "In our study, we observed an increase in TFRC expression and a decrease in FTH1 expression in gliomas following orexin‐A treatment." (PMID 38685674, 2024). "LncTUG1 targets MYC-associated zinc finger protein (MAZ) to reduce FTH1 expression and then enhances DHA-induced ferroptosis in glioma cells." (PMID 37686142, 2023). "For the first time, we demonstrated that upregulated FTH1 expression in DHA treated glioma cells which weakened the ferroptosis." (PMID 36164395, 2022). "Tumor FTL levels were associated with prognosis in patients with lower grade glioma (LGG), whereas FTH1 levels were associated with prognosis in patients with liver hepatocellular carcinoma, HNSC, LGG, and kidney renal papillary cell carcinoma." (PMID 33864445, 2021). "One study found that the growth of C6 glioma cells was significantly reduced when FTH1 expression was dramatically increased." (PMID 26517988, 2015). "Currently, siRNA, miRNA, piRNAs and other carriers can be effective tools for targeted FTH1 in the tumor (Balaratnam, West & Basu, 2018), of which H-ferritin siRNA has achieved initial success in improving the curative effect of gliomas in patients receiving chemotherapy." (PMID 38025726, 2023). "However, we were surprised to find FTH1 expression was significantly increased in DHA treated glioma cells, which contradicts the fact that DHA promotes ferroptosis." (PMID 36164395, 2022). "Also, the protein expression level of NCOA4 was increased in MXRA8 knockdown glioma cells, while FTH1 was reduced." (PMID 35281049, 2022). "Likewise, our study also demonstrated that inhibition of MXRA8 increased the protein expression of NCOA4 and decreased FTH1 protein levels in glioma cells." (PMID 35281049, 2022). "Furthermore, we integrated the FTH1-mediated TfR upregulation mechanism with Tf-modified drug-loaded liposomes (Tf-LPD) for targeted therapy, achieving a unified diagnostic and therapeutic approach for gliomas." (PMID 40723232, 2025). "PLP1, FTH1, and GM42418 were validated as potential molecular biomarkers, providing novel insights into glioma pathogenesis and potential therapeutic targets." (PMID 42283031, 2026).